INS (insulin)
Diseases named in the same sentence as INS in open-access papers (continued):
Sharing a sentence is not in itself a finding about the gene and the disease.
diabetes (continued). "The high fat diet (HFD) mouse is a widely used model for studying insulin-resistant in diabetes." (PMID 37396164, 2023). "We analyzed the impact of insulin-treated compared to non-insulin-treated diabetes mellitus in patients undergoing PCI of a de novo lesion on the outcome of drug-coated balloons versus drug-eluting stents in the diabetic population of the randomized BASKET-SMALL 2 trial." (PMID 36975883, 2023). "In the case of diabetes, the β-cells of the pancreas exhibit impaired secretion of insulin." (PMID 37388336, 2023). "Type 1 diabetes mellitus (T1DM) is caused by the autoimmune-mediated destruction of insulin-producing cells (IPCs) and still has no effective cure." (PMID 38813509, 2023). "GIP is one of the incretin hormones, located in the β-cells, adipose tissue & in brain where it plays an important role in the type-2 diabetes mellitus and other metabolic disorders by boosting the insulin response which is triggered by the post-prandial rise in glycemia." (PMID 36782201, 2023). "It is well known that insulin sensitivity is decreased in type 2 diabetes mellitus." (PMID 37043764, 2023). "This system in combination with the continuous and simultaneous monitoring of glucose and insulin as the two key diabetes biomarkers could offer the ultimate solution to diabetes management." (PMID 37504117, 2023). "This double-blind placebo-controlled clinical trial tests the hypothesis that POA increases insulin sensitivity and decreases hepatic lipogenesis in overweight and obese adult subjects with pre-diabetes." (PMID 38313838, 2023). "However, during the study, the two who developed diabetes despite dapagliflozin treatment were started on glucose-lowering therapy (one on basal insulin and one on metformin)." (PMID 37202813, 2023). "The mild progression of diabetes, combined with feeding difficulties and, most importantly, the occurrence of spontaneous, ultimately unexplained hypoglycemic episodes, led to the decision to postpone initiation of insulin therapy at this stage." (PMID 37580732, 2023). "A1 AR selective agonist, 2-chloro N6 -cyclopentyladenosine (CCPA), has been shown to alleviate diabetes by increasing insulin = stimulated glucose transport in isolated rat muscle, and thus ruled out the possible protective effect of A1 AR antagonist against diabetes." (PMID 37143025, 2023). "In this work, the liver and serum samples were collected from offspring born to a genetically engineered diabetic pig model for mutant INS gene-induced diabetes of youth (MIDY) (PHG) and from offspring born to WT littermate controls (PNG), according to the principles of systematic random sampling." (PMID 37414142, 2023). "Type 2 diabetes mellitus (T2DM) is a chronic metabolic illness in which the patient’s capability to produce sufficient amounts of insulin is diminished or patients display insulin resistance; thus, the capability of insulin to accomplish its normal function becomes disrupted." (PMID 38001474, 2023). "Insulin continues to be an important part of diabetes management." (PMID 36902639, 2023). "In addition, Metformin group, although not on vitamin B12 supplementation, had higher level of total vitamin B12 (p = 0.028), Metformin and Insulin group were more likely to have family history for diabetes (p = 0.019)." (PMID 36793288, 2023). "Consequently, it is reasonable to conclude that the treatment of diabetes and its consequences depends on the replenishment of insulin-producing pancreatic β-cells, thereby addressing the limitations of present therapeutic approaches." (PMID 36932309, 2023). "Furthermore, low HDL levels have commonly been associated with diabetes in humans, with HDL shown to increase insulin secretion and β-cell survival." (PMID 37255970, 2023). "Type 1 Diabetes Mellitus (T1DM) is a chronic autoimmune disease related to an immune system alteration that destroys pancreatic ß cells with a consequent quantitative or qualitative dysfunction of insulin." (PMID 37895163, 2023).
diabetes (continued). "T2DM impacts insulin gene expression and beta cell development in diabetic islets through histone modifications and DNA methylation, critical for modulating mitochondrial genes to regulate diabetes." (PMID 38198642, 2023). "It is known that insulin released by pancreatic islet b cells promotes glucose uptake by hepatocytes and conversion into hepatic glycogen for storage, whereas insulin resistance in the liver of patients with type 2 diabetes mellitus (T2DM) leads to poor glycemic control." (PMID 39188562, 2023). "However, in HNF1B-MODY there is a combination of insulin deficiency and hepatic insulin resistance, explaining why they often require insulin therapy in the first years after diabetes diagnosis." (PMID 36793123, 2023). "However, these concentrations decreased as glucose regulation worsened, which implies that in addition to insulin resistance, there was a reduction in the ability of the individuals to secrete insulin, corresponding to a worsening of diabetes." (PMID 37089422, 2023). "For those with diabetes, insulin levels which are insufficient to facilitate the uptake of glucose into cells and/or insulin resistance may result in higher values in VPG." (PMID 37687871, 2023). "Which patient with type 2 diabetes mellitus requires insulin?" (PMID 37132569, 2023). "Furthermore, zinc supplementation has demonstrated curative effects on diabetes, including the correction of glycaemia, improvements in pancreatic cell function, and the promotion of insulin synthesis and secretion." (PMID 37887373, 2023). "Furthermore, the progressive inability of beta-cells to preserve the overproduction of insulin triggers the clinical onset of glucose intolerance and type 2 diabetes mellitus." (PMID 36979649, 2023). "We investigated whether pharmacologic myostatin inhibition in a mouse model of insulin‐deficient, streptozotocin (STZ)‐induced diabetes is protective for bone and skeletal muscle." (PMID 38025035, 2023). "To investigate whether pancreatic β cells secrete insulin in an ex vivo model, we cultured each different 3D organoid nanomaterial dishes from groups treated with various diabetes-induced stresses." (PMID 37134105, 2023). "We aimed to explore whether the unmethylated/methylated ratio of the insulin and amylin genes might be a good biomarker of β cell death in different types of diabetes." (PMID 37264478, 2023). "The main pharmacological treatment for diabetes was premixed insulin (55, 94.8%)." (PMID 38504754, 2023). "Moreover, polyamines have a time- and concentration-dependent inhibitory effect on the protein phosphatase activity of insulin-secreting cells in diabetes." (PMID 36771224, 2023). "These devices are especially important for people with diabetes treated with insulin therapy." (PMID 37736430, 2023). "In the diabetes attitudes, wishes and needs second study (DAWN), participants reported low confidence in the efficacy of insulin, with 26.9% of participants abstaining from insulin because they thought insulin unfeasible or impracticable to manage their diabetes." (PMID 38076524, 2023). "Diabetes is characterized by a high blood glucose level and is usually treated or maintained by lowering blood glucose levels through vigorous diet regimes, insulin injections, supplementing insulin secretion, and increasing insulin sensitivity." (PMID 36677933, 2023). "However, visceral fat tends to accumulate, which, combined with decreased insulin secretion from pancreatic beta cells, leads to the development of diabetes." (PMID 37103055, 2023). "Importantly, fasting blood glucose (p = 0.261) and circulating concentrations of insulin (p = 0.619) were similar throughout the menstrual cycle in patients with diabetes." (PMID 37679748, 2023). "Insulin, Linagliptin, and levetiracetam were used for diabetes and seizures." (PMID 37363571, 2023).
diabetes (continued). "The October 1923 award of the Nobel Prize in Physiology or Medicine to FG Banting and JJR Macleod ignored Paulescu's scientific achievements in the treatment of experimental diabetes and rewarded the extraordinary advance of insulin treatment in human diabetes." (PMID 37407772, 2023). "Consequently, there is no official recommendation in the ADA’s Standards of Medical Care in Diabetes Technology-2023 for using CGM in insulin-treated older adults with T2DM." (PMID 37993898, 2023). "The imbalance of free radicals and antioxidants lead to oxidative stress and the decrease of peripheral insulin sensitivity, induce the production of inflammatory factors, and then promote the occurrence and development of diabetes and its complications by regulating IR." (PMID 37822878, 2023). "Taken together, these data suggest that the rescue of diabetes in IRS2-null mice by Cdk4-R24C was due to correction of insulin deficiency rather than insulin responsiveness." (PMID 37712417, 2023). "Rodents are frequently studied over 4–12 weeks of diabetes and, to ensure a good clinical condition during the entire experiment, diabetic animals may receive regular low-dose insulin injections." (PMID 37509563, 2023). "However, given the difficulty of matching carbohydrate intake with insulin dose, reducing dietary carbohydrate consumption among people with diabetes has become a common dietary pattern." (PMID 36986149, 2023). "Therefore, the evaluation of the morphology, size, and insulin secretion activity of islets within pancreatic tissue is recognized as a crucial factor for the treatment of diabetes." (PMID 37623224, 2023). "The response in glucose, glucagon and PYY was higher among participants with T2D, compared to participants with pre-T2D, with either pre-load (e.g. p-value for the multiplicative interaction between diabetes status and the swallowed pre-load was 0.01 for glucose and <0.001 for insulin)." (PMID 37624823, 2023). "An appropriate glycemic control seems to decrease the risk of HCC; however, the effect of each diabetes therapy is contradictory, since some studies have found a benefit for metformin but not for insulin or sulfonylureas." (PMID 37444477, 2023). "In the long term, this could prove to be a disadvantage for diabetic patients, particularly those with type 1 diabetes mellitus, who are absolutely dependent on insulin injections for the treatment of diabetes." (PMID 36770820, 2023). "In our cohort, there is found a statistically significant difference in the average frequency of use of words related to COVID-19 (i.e., “lockdown”, “social distancing”, “to get sick with COVID-19”) and to “T1D” words (i.e., “glycemia”, “diabetes”, “insulin”) [t23 = 1.98, p < 0.05]." (PMID 36767985, 2023). "Diabetes mellitus (DM) is a chronic and significant medical condition characterized by inadequate production of insulin by the body or the inability to effectively utilize the insulin it produces, its prevalence has reached alarming levels, making it a major health concern." (PMID 37697301, 2023). "However, there are few reports on A. galanga responsible for increasing insulin secretion and inhibiting α-glucosidase activity, which can ultimately prevent or delay diabetes." (PMID 36771665, 2023). "Insulin is commonly used in type 2 diabetes mellitus (T2DM) to achieve glycemic control." (PMID 37542280, 2023). "However, studies in recent years have found poor adherence in patients with T2D who use insulin to treat their diabetes." (PMID 37654567, 2023). "Therefore, maintaining the stability of insulin levels and blood glucose is the key point for diabetes, but increase the insulin levels and glucose metabolism in the brain is more important in AD." (PMID 36978970, 2023). "Adequate insulin production, insulin sensitivity, glucose intake, along with a variety of other endocrine factors (glucagon like peptide-1, glucagon) establish glycemic control and are related to diabetes severity." (PMID 37509016, 2023).
diabetes (continued). "The patients on insulin therapy probably had uncontrolled diabetes which may account for the relatively better self‐care practice." (PMID 36464636, 2023). "used this exact analog in 2013 in patients with obesity and diabetes, where the drug could also reduce insulin levels." (PMID 37948566, 2023). "The most common form of diabetes is type 2 diabetes (T2D), which usually appears in adulthood when the body becomes insulin resistant and the beta cells are unable to adapt to this reduced insulin sensitivity." (PMID 36830064, 2023). "Since hepatic steatosis has been regarded as a driving force for insulin resistance and type 2 diabetes mellitus, the improved insulin sensitivity by TRIM21 could ameliorate hepatic glucose and lipid metabolic disorders by ubiquitination of FASN expression." (PMID 37249651, 2023). "Some of the mechanisms we can invoke for boys with type 1 diabetes having a lower LV mass when compared to boys without diabetes relate to cardiomyocyte growth and development and its association with insulin." (PMID 40303256, 2023). "Evaluation of motivation, serenity in life with diabetes, awareness of own diabetes practices, diabetes empowerment, diabetes loneliness, and diabetes distress are applicable, feasible, and appropriate when measuring the effect of peer support on adults with insulin-pump-treated diabetes." (PMID 37629520, 2023). "Diabetes mellitus was present in 29% of the patients (11% insulin-dependent)." (PMID 38299080, 2023). "Hyperglycemia in diabetes results from the insufficient action of insulin." (PMID 37372995, 2023). "For those with diabetes, having access to affordable medications, especially insulin, is essential." (PMID 38022000, 2023). "The beta cells are damaged by free radicals, which reduces the generation of insulin and may make diabetes more difficult to treat." (PMID 36838577, 2023). "Triterpenoids, particularly the lupane-type, may be a promising therapeutic drug for diabetes because of their diverse biological actions, which include effects on glucose uptake and absorption, diabetic vascular dysfunction, and insulin secretion." (PMID 37509141, 2023). "Diabetes mellitus (DM) comprises a group of metabolic diseases characterized by an increase in plasma glucose levels (hyperglycemia) due to defects in the secretion (type 1 DM or T1DM) or action (type 2 DM or T2DM) of insulin." (PMID 37250131, 2023). "Improving the health-related quality of life for adolescents is an important priority during the transition from paediatric to adult healthcare, which beyond the medical supervision of insulin regimens requires attention to diabetes education, social support, and psychological services." (PMID 38420040, 2023). "Thus, maintaining fiber intake at the observed levels, and increasing dietary fiber intake must be emphasized in the nutrition therapy for diabetes prevention and insulin management." (PMID 37960272, 2023). "Moreover, this non-destructive method benefits not only for assessing the capacity of insulin secretion and early diagnosis of diabetes but also provides a strategy for soft tissue imaging, such as brain and tumour analysis." (PMID 36718155, 2023). "Diabetes mellitus (DM) is a group of metabolic disorders characterized by chronic hyperglycemia and perturbed metabolism of carbohydrates, lipids, and proteins, resulting from defects in insulin secretion and action." (PMID 36950696, 2023). "For example, insulin signaling dysregulation may contribute to developing diabetes in COVID-19 patients." (PMID 37830426, 2023). "Therefore, Gla-300 seems to be a promising insulin therapy for diabetes management in people fasting during the Ramadan period." (PMID 36624651, 2023). "Type 1 diabetes mellitus (T1DM) is an autoimmune disease in which antibodies and T cells target a range of host autoantigens associated with beta cell production of insulin (INS), resulting in loss of INS production and consequent hyperglycemia." (PMID 37176044, 2023).
diabetes (continued). "Wearable insulin biosensors can be integrated with telemedicine and remote monitoring systems, enabling healthcare providers and caregivers to support individuals with diabetes from a distance." (PMID 38239544, 2023). "Possibly, patients with already known diabetes, previous insulin therapy, and low baseline HbA1c values are prone to more intensive therapies during hospital admission, favoring hypoglycemia, although this hypothesis should be tested in future studies." (PMID 38044455, 2023). "Studies using non-pregnant animal models of obesity and diabetes have demonstrated that the inclusion of butyrate and propionate in the diet leads to reduced body weight, obesity, fasting glucose and insulin levels, improved insulin tolerance, and amelioration of diabetes symptoms." (PMID 37600950, 2023). "Only permanent insulin-releasing devices will save millions of patients with diabetes." (PMID 37623676, 2023). "Frequent glucose monitoring is recommended for patients treated with insulin – all patients with type 1 diabetes mellitus (T1D) and some patients with type 2 diabetes mellitus (T2D) - so they can adjust insulin dose, depending on factors such as diet and exercise." (PMID 36574148, 2023). "Regarding self-care activities, higher adherence was observed in the activities: Taking insulin injections as recommended (6.7); Taking diabetes medications as recommended (6.5); Taking the indicated number of diabetes pills (6.5); and Following a healthy diet (4.8)." (PMID 37436236, 2023). "Structured education in flexible insulin therapy and use of diabetes technologies (insulin pumps and glucose sensors) may reduce severe hypoglycaemia episodes, and education may improve IAH without increasing HbA1c." (PMID 36538062, 2023). "HDACs and sirtuins play key roles in diabetes by affecting insulin signaling and secretion." (PMID 37143582, 2023). "UCP2 may be a promising therapeutic target for treating type 2 diabetes mellitus because it regulates insulin secretion and beta-cell dysfunction." (PMID 36770960, 2023). "Hence, this study aimed to assess the impact of COVID-19 on glycemic control among children with T1DM on insulin pump in Egypt and to explore it’s relation to various clinico-demographic parameters and acute diabetes complications." (PMID 38012643, 2023). "Polyphagia and polydipsia are symptoms of diabetes mellitus that are caused by insulin deficiency or the lack of insulin utilization by target organs." (PMID 37396152, 2023). "Additionally, nutritional fat consumption reduces glucose utilization mediated by insulin and endorses insulin resistance in diabetics." (PMID 37089941, 2023). "For example, in our study, the only signs of LUTD that was reported in these dogs was inappropriate urination and was reported because of poorly regulated or newly diagnosed diabetes mellitus in most of the dogs and resolved with initiation of insulin treatment or adjustments in insulin treatment." (PMID 36708199, 2023). "For pump initiation, our patients were required to attend a pre–pump use class (during which they learned about insulin pump therapy and various device options) and complete a pre–pump use checklist, which included a skills assessment on various aspects of diabetes management." (PMID 37294607, 2023). "However, it should be noted that in diabetes, decreased insulin secretion or insulin resistance leads to increased blood glucose." (PMID 36978970, 2023). "The results of our study build up evidence regarding the need to avoid hypoglycemia and be cautious regarding the use of insulin and other antidiabetic agents with hypoglycemic potential (e.g., sulfonylureas), particularly in patients with diabetes seeking tight glycemic control." (PMID 37876724, 2023). "For example, if measuring a trainee’s rate of ordering long-acting insulin for patients with diabetes mellitus, measuring hypoglycemic events that might result from over-ordering of insulin would be an important balancing measure." (PMID 37215538, 2023).